Y_RNA (Y RNA )
Gene: Miscellaneous RNA gene on chromosome 1 (114,490,724 to 114,490,832, forward strand). Ensembl gene ENSG00000201114.
Homologues: Orthologues: chimpanzee Y_RNA (100% identical), rat Y_RNA (64% identical). Paralogues in human: RNY1 (86% identical), Y_RNA (83% identical), Y_RNA (82% identical), Y_RNA (81% identical), Y_RNA (80% identical), RNY1P10 (79% identical), RNY1P7 (79% identical), RNY1P8 (79% identical), Y_RNA (79% identical), RNY1P11 (78% identical), Y_RNA (78% identical), Y_RNA (77% identical), and 95 more.